DDX23 (DEAD-box helicase 23)
Diseases named in the same sentence as DDX23 in open-access papers (continued):
Sharing a sentence is not in itself a finding about the gene and the disease.
cancer (8 papers, 2021 to 2025). A tumor composed of atypical neoplastic, often pleomorphic cells that invade other tissues. "And recurrent somatic mutations or expression dysregulation of several U5 snRNP proteins, including DDX23 were reported to be associated with human cancers." (PMID 36977668, 2023). "Notably, DDX23 is a spliceosomal enzyme that is highly expressed in most cancers and is closely associated with several biological behaviours of tumour cells." (PMID 41360761, 2025). "However, somatic mutations in PRPF8 have now been linked to myeloid neoplasms, while altered expression levels of several other U5 snRNP proteins (PRPF6, EFTUD2, SNRNP40, and DDX23) have been associated with human cancer." (PMID 33584830, 2021). "The forced silence of METTL3 and DDX23 led to suppressed cancer phenotypes and in vivo malignancy, showing the potential of METTL3/DDX23 axis as therapeutic targets for PDAC." (PMID 36977668, 2023). "To summarize, METTL3 modified DDX23 mRNA in an m6A modification manner thus promoting cancer cell proliferation, mobility, and chemoresistance through PI3K/Akt signaling." (PMID 36977668, 2023). "Remarkably, DDX23 has been discovered as a component of the U4/U6-U5 tri-snRNP complex involved in pre-mRNA splicing in cancer progression." (PMID 33990545, 2021). "The knockdown of DDX23 led to suppressed cancer malignancy, and tumor growth and metastasis." (PMID 36977668, 2023). "Therefore, DDX23 is differentially expressed and demonstrates different roles in various human cancers." (PMID 36977668, 2023). "In addition, the knockdown of DDX23 resulted in inhibited cancer cell proliferation and mobility as well as resistance to GEM." (PMID 36977668, 2023). "Furthermore, recurrent somatic mutations or changes in the expression levels of a number of U5 snRNP proteins (PRPF6, PRPF8, EFTUD2, DDX23, and SNRNP40) have been associated with human cancers." (PMID 33584830, 2021). "Furthermore, the pri-miRNA processing function of DDX23 has been investigated in human cancers." (PMID 38689093, 2024). "So far, how DDX23 is regulated and participates in cancer genesis has remained largely unknown." (PMID 36977668, 2023). "Besides, in all the 32 cancer types of the TCGA database, METTL3 and DDX23 demonstrated significantly positive correlations." (PMID 36977668, 2023). "The role of DDX23, on the other hand, has not been elucidated clearly in cancers." (PMID 36977668, 2023). "Again, this link between DDX23 and cancer is not related to its function in the spliceosome and argues that extra-spliceosomal functions of certain U5 proteins could potentially play a role in their pathogenesis." (PMID 33584830, 2021).
tumor (5 papers, 2021 to 2025). "DDX23 mRNA was significantly upregulated in tumor tissues compared with the tumor-adjacent tissues (data obtained from the publicly available source)." (PMID 36977668, 2023). "DDX23 knockdown led to significantly smaller tumor size, lighter tumor weight, and smaller tumor volume in synergy with GEM treatment." (PMID 36977668, 2023). "Xenograft and animal lung metastasis experiments were also conducted to study the functional role of METTL3 or DDX23 on tumor growth and lung metastasis in vivo." (PMID 36977668, 2023). "The H&E pathology and IHC analysis of tumor tissues also demonstrated that DDX23 silence resulted in less intense Ki-67 staining." (PMID 36977668, 2023). "The tumor weights of NC group were significantly higher than those of DDX23 knockdown group (P < 0.05)." (PMID 34966670, 2021). "Functional assays indicated that DDX23 silencing significantly impeded cell proliferation/invasion in vitro and tumor growth in vivo." (PMID 34966670, 2021). "IHC staining showed that Ki-67 expression was decreased in xenograft tumors of shDDX23-treated mice group, indicating that DDX23 knockdown reduced the proliferation activity of tumor cells in vivo." (PMID 34966670, 2021). "On the one hand, this reflects the enhanced metabolic activity and increased mRNA synthesis characteristic of tumour cells, and on the other hand, suggests that DDX23 may influence the synthesis of multiple mRNAs." (PMID 41360761, 2025). "Additionally, METTL3 knockdown inhibited PDAC aggressive tumor phenotypes through, at least in part, by weakening DDX23 mRNA m6A modification." (PMID 36977668, 2023). "By increasing the local concentration of the enzyme DDX23 within the spliceosome, LncPEDS1-AS promotes the expression of the sense-strand mRNA PEDS1, diminishing the sensitivity of tumour cells to ROS accumulation." (PMID 41360761, 2025). "Our findings establish a potential tumor promotive and chemo-resistant role for METTL3/DDX23 axis in PDAC." (PMID 36977668, 2023). "Besides of that, DDX23 depletion resulted in significantly suppressed phosphorylated PI3K and Akt expression in xenograft tumor tissues." (PMID 36977668, 2023).
neurodevelopmental disorder (2 papers, 2024 to 2025). A behavioral and cognitive disorder with onset during the developmental period that involves impaired or aberrant development of intellectual, motor, or social functions. "This approach has identified an association of DDX23 variants to a neurodevelopmental disorder." (PMID 40264708, 2025).
DDX23 also shares sentences with these, for which no sentence is quoted: pancreatic ductal adenocarcinoma (2 papers); brain malformations (1); breast carcinoma (1); developmental delay (1); lung carcinoma (1); polymicrogyria (1); prion disease (1); prostate carcinoma (1); renal cell cancer (1).